FOXM1 (forkhead box M1)
Diseases named in the same sentence as FOXM1 in open-access papers (continued):
Sharing a sentence is not in itself a finding about the gene and the disease.
glioma (continued). "Although previous studies have put forth that TRIM56 can suppress the radio-sensitization of GBM by regulating the FOXM1-mediated DNA repair, the function of TRIM56 in glioma has not been sufficiently studied." (PMID 36870986, 2023). "This demonstrated a significant overexpression of MYBL2, FOXM1, ETS1, HIF-1A, and JUN in both glioma cohorts compared to non-neoplastic brain tissues." (PMID 35228525, 2022). "In another study, GLI1-3 expression, along with its target genes, FOXM1 and BMI1, were present in all the tested glioma cell lines in contrast to normal brain tissue that lacked GLI1 expression." (PMID 35409080, 2022). "The absence of FOXM1 corresponds to lowered VEGF in vitro, and, in mouse experiments, glioma cells with FOXM1 inhibited were found to have lower VEGF than their counterparts." (PMID 34948433, 2021). "In contrast, there is no specific enrichment with a FOXM1 antibody at the promoters of H19, myoglobin and CCND1 3 which are genes non-expressed or imprinted in glioma cells (they serve as negative controls)." (PMID 34131149, 2021). "The expression of FOXM1 and NOX4 was increased in glioma specimens compared with normal brain tissues and correlated with poor clinical outcomes." (PMID 34740322, 2021).
gastric cancer (147 papers, 2007 to 2025). A primary or metastatic malignant neoplasm involving the stomach. "Further studies demonstrate that RNF112 plays a tumor-suppressor role by targeting FOXM1, whose expression is negatively associated with that of FOXM1 in gastric cancer." (PMID 37288663, 2023). "Regarding to the tumor types, elevated FOXM1 expression in tumor tissues were associated with worse OS of most human solid tumors, such as colorectal cancer, gastric cancer, hepatic cancer, lung cancer and ovarian cancer." (PMID 28427178, 2017). "Subgroup analysis showed that FOXM1 overexpression was associated with poor prognosis of colorectal cancer, gastric cancer, hepatic cancer, lung cancer and ovarian cancer." (PMID 28427178, 2017). "To further validate the molecular mechanisms underlying Cath-D-induced metastasis in gastric cancer, we detected the expression of E-cadherin in FOXM1-OE and FOXM1-OE-Cath-D-KD cells using western blotting analysis." (PMID 28978107, 2017). "Spearman correlation analysis revealed that Cath-D expression was obviously positively associated with FOXM1 expression in gastric cancer tissues (R2=0.653, p=0.011)." (PMID 28978107, 2017). "To further confirm that association, we detected the expression levels of FOXM1 and Stathmin in gastric cancer tissues." (PMID 24628949, 2014). "Taken together, these findings suggest that the RNF112/FOXM1 axis could potentially serve as a diagnostic and therapeutic biomarker for gastric cancer." (PMID 37288663, 2023). "Consistent with luciferase assay, the expression of Cath-D protein was also positively associated with the expression of FOXM1 in gastric cancer tissues, and its expression was also obviously decreased in FOXM1-knockdown SGC7901 and MKN28 cells, suggesting that Cath-D is a direct target of FOXM1." (PMID 28978107, 2017). "In conclusion, the loss of GPC3 causes an up-regulation of FoxM1 in gastric cancers." (PMID 27259271, 2016). "Moreover, the association of FOXM1 expression and chemosensitivity to docetaxel in gastric cancer cells was further explored." (PMID 24004449, 2013). "Interestingly, RNF112 was most negatively associated with FOXM1 in gastric cancer tissues." (PMID 37288663, 2023). "FOXM1 is a transcription factor that promotes tumorigenesis, uncontrolled cell growth, and epithelial-mesenchymal transition; it has been linked to the progression of ovarian cancer, colorectal cancer, triple negative breast cancer, non-small cell lung cancer, and stomach cancer." (PMID 28187428, 2017). "FOXM1 is a well-known cell cycle regulator frequently upregulated in cancers; our finding that FOXM1 is elevated in PGC is in line with its association with advanced disease and poor outcomes in gastric cancer." (PMID 40862793, 2025). "Previous studies have found that RNF112 possesses an autoubiquitination feature and also directly ubiquitinates TDP-43 and Forkhead box M1 (FOXM1) to attenuate related neuropathy and inhibit gastric cancer progression, respectively (15, –17)." (PMID 40198702, 2025). "A recent study reported that KIAA1429 promotes m6A methylation of FOXM1, leading to chemoresistance in gastric cancer." (PMID 40301310, 2025). "For example, in gastric cancer, upregulation of FOXM1 contributes to disease progression by regulating key processes such as the cell cycle and epithelial-mesenchymal transition (EMT) signaling." (PMID 38373993, 2024). "As gastritis progresses to gastric cancer, the oncogenic transcription factor Foxm1 becomes increasingly expressed." (PMID 38014984, 2024). "Panobinostat blocked the Akt/FOXM1 signaling pathway to inhibit gastric cancer cell proliferation and metastasis." (PMID 39068665, 2024).
gastric cancer (continued). "The knockdown of KIAA1429 sensitized gastric cancer cells to cisplatin treatment by increasing oncogene FOXM1 (Forkhead box M1) expression." (PMID 39456252, 2024). "In GF INS-GAS mice infected with H. pylori, coinfection with C. acnes inhibited Foxm1 elevation, which is a key step in the progression of gastritis to gastric cancer." (PMID 38014984, 2024). "FOXM1 is a pro-oncogenic transcription factor overexpressed in many cancers, including H. pylori-induced gastric cancer (5, –, 7)." (PMID 38014984, 2024). "For instance, HULC was found to interact with FoxM1 and modulate the protein level of FoxM1 by inhibiting its ubiquitination process and stabilizing its expression, thereby mitigating cisplatin resistance in gastric cancer." (PMID 38927012, 2024). "YTHDF1 is recruited by KIAA1429 to the transcription factor FOXM1 to stabilize FOXM1 mRNA and thus regulate cisplatin sensitivity in gastric cancer cells." (PMID 39060874, 2024). "The regulatory function of TEAD4, ETV4, PRRX1, and FOXM1, over other key TFs and common DEGs, was highlighted in gastric cancer, establishing key co-regulatory complexes." (PMID 39228892, 2024). "A recent study demonstrated that overexpressed PLAU in tumor tissues synergizes with FOXM1 to promote gastric cancer progression." (PMID 38988712, 2024). "Of particular note, the role of KIAA1429 upregulating FOXM1 through m6A modification has been observed only in gastric cancer." (PMID 39060874, 2024). "FOXM1 and RNF112 are both associated with the proliferation and invasion signaling pathways in gastric cancer." (PMID 37288663, 2023). "RNF112 suppresses the malignancies of gastric cancer cells by suppressing the FOXM1 transcriptional network in vitro." (PMID 37288663, 2023). "Although several E3 ligases have been identified, here, via ON-TARGETplus siRNA library–based approaches, an E3 ubiquitin ligase, RNF112, was identified as promoting the ubiquitination and degradation of FOXM1 in gastric cancer." (PMID 37288663, 2023). "The result showed that a significant correlation was found between KMT2A and the stemness-related gene sets, including tumor stemness-related signature (CD44/CD133/Sox2/OCT4) and gastric cancer-specific stemness signature (Sox/FOXM1)." (PMID 38025523, 2023). "A recent study demonstrated that hyperactivation of FOXM1 can maintain low levels of ROS in gastric cancer, which, in turn, ensures the survival of stem cells present in gastric cancer and induces chemotherapy resistance." (PMID 37288663, 2023). "The distribution of the patients with gastric cancer based on FOXM1 and RNF112 expression was revealed by t-distributed stochastic neighbor embedding analysis." (PMID 37288663, 2023). "Taken together, our results demonstrate that RNF112, a neurodevelopment-related protein, plays a promising antitumor role in gastric cancer by inducing the ubiquitination and degradation of oncoprotein FOXM1." (PMID 37288663, 2023). "Long non-coding RNA, TRPM2-AS mediated FOXM1 overexpression led to development of radio resistance in gastric cancer cells." (PMID 37025658, 2023). "Altogether, we demonstrate that RNF112 suppresses gastric cancer progression by ubiquitinating FOXM1 and highlight the RNF112/FOXM1 axis serves as both prognosis biomarker and therapeutic target in gastric cancer." (PMID 37288663, 2023). "Previously, FOXM1 was identified as one of the targets of miR-4521 in medulloblastoma and gastric cancer." (PMID 37025658, 2023). "As a result, RNF112-Mut was unable to interfere with FOXM1 downstream genes and almost lost its tumor suppressor roles in gastric cancer." (PMID 37288663, 2023). "Of note, mechanism study revealed that RNF112 directly ubiquitinates FOXM1 in gastric cancer, resulting in a decreased FOXM1 transcriptional network and suppressing the proliferation and invasion of gastric cancer." (PMID 37288663, 2023).
gastric cancer (continued). "SENP6 activates and stabilizes FOXM1 by catalyzing the de-SUMOylation of FOXM1, which leads to successful mitosis and promotes the growth of gastric cancer cells." (PMID 37777749, 2023). "Because of the carcinogenic roles of FOXM1 in gastric cancer, ectopic expression of RNF112 markedly inhibited the proliferation and invasion of MGC803 and BGC823 cells." (PMID 37288663, 2023). "PLAU and CTSK have been shown to play a role in various tumors, with PLAU being considered as a potential biomarker in head and neck squamous cell carcinoma, promoting the EMT process, and tumor development in gastric cancer by cooperating with FOXM1." (PMID 38077303, 2023). "In gastric cancer patients, overexpression of FOXM1 was related to cisplatin resistance, and depletion of FOXM1 improved this resistance." (PMID 36291811, 2022). "In gastric cancer, miR-149-5p has an anti-metastatic property by suppressing forkhead box M1 (FOXM1) expression." (PMID 35055115, 2022). "For example, miR-612 was bound by TRPM2-AS in gastric cancer to increase FOXM1 expression and enhance radiotherapy resistance of gastric cancer." (PMID 36262872, 2022). "Inhibition of miR-877-5p promoted migration and invasion of gastric cancer cells via binding to FOXM1." (PMID 36438895, 2022). "The FBXL2 protein also interacts with the forkhead box M1 (FoxM1) transcription factor in gastric cancer, with ubiquitinates Aurora B to inhibit tumorigenesis." (PMID 36553463, 2022). "FOXM1 is a transcription factor and plays a crucial role in different types of cancers, including gastric cancer, lung cancer and prostate cancer." (PMID 35524313, 2022). "Mechanistically, KIAA1429 regulated the sensitivity of gastric cancer cells to cisplatin by stabilizing FOXM1 mRNA via YTHDF1." (PMID 36291811, 2022). "Collectively, we found that gastric cancer cells acquired cisplatin resistance by enhancing FOXM1 mRNA stability via KIAA1429 catalyzed m6A modification." (PMID 36291811, 2022). "In conclusion, our results demonstrated that KIAA1429 facilitated cisplatin resistance by stabilizing FOXM1 mRNA in gastric cancer cells." (PMID 36291811, 2022). "For example, miR-194 inhibits the migration, invasion, and epithelial-mesenchymal transition (EMT) of gastric cancer cells by downregulating FoxM1." (PMID 34127010, 2021). "FOXM1 expression was low in quiescent cells but elevated in most tumors, including liver cancer and gastric cancer." (PMID 34712733, 2021). "FOXM1 was also found to transactivate LDHA in gastric cancer, promoting a glycolytic phenotype with high proliferative, migratory, and invasive abilities." (PMID 34205406, 2021). "A recent study demonstrated a positive feedback loop between lncRNA-PVT1 and FOXM1 in gastric cancer." (PMID 33842324, 2021). "Overexpression of FoxM1 increased MMP-2 and MMP-9 expression, while knockdown of FoxM1 by siRNA inhibited gastric cancer cell proliferation and migration to the same extent as Tan IIA." (PMID 34819867, 2021). "A state-of-art work indicated that PLAU, which is overexpressed in tumor tissues, functioned collaboratively with FOXM1 in the promotion of gastric cancer progression." (PMID 34244472, 2021). "miR-149 has also been shown to repress FOXM1 expression in non-small-cell lung cancer and gastric cancer." (PMID 34205406, 2021). "Studies in gastric cancer and pan-cancer have suggested that lncPVT1 can also interact with and stabilize the FOXM1 protein and have shown that FOXM1 binds to the promoter of lncPVT1 to activate its transcription." (PMID 34205406, 2021). "The expression levels of ETS1, IGF2, FOXM1 and E-cadherin were detected by qRT-PCR in the collection of human gastric carcinoma specimens and adjacent normal tissues (cohort A)." (PMID 33407516, 2021). "Meanwhile, a positive correlation between TRPM2-AS and IGF2BP1 (R = 0.5415, P = 0.01) was found in 20 paired gastric cancer tissues, as well as between FOXM1 and TRPM2-AS (R = 0.5056, P = 0.02)." (PMID 32123162, 2020).
gastric cancer (continued). "FRLnc1, a long non coding RNA has been shown to be upregulated in 49% (20/41) of gastric cancer cases by positively regulating the expression of FOXM1 leading to enhanced cell migration." (PMID 33680951, 2020). "Previously, we found that overexpression of FOXM1 and PLAU were associated with gastric cancer progression and poor prognosis." (PMID 31949481, 2020). "PVT1 transcript levels changes upon manipulation of FOXM1 protein expression in gastric cancer cells." (PMID 32083000, 2020). "Two binding sites for FOXM1 (a transcriptional factor that promotes oncogenesis) was found on the promoter region of PVT1 in gastric cancer cells." (PMID 32117705, 2020). "Positive correlation between PTTG3P and FoxM1 were also observed in liver cancer (R = 0.593, P = 0.000), colorectal cancer (R = 0.341, P = 0.000) and gastric cancer (R = 0.900, P = 0.000) tissues by analyzing TCGA and GEO databases." (PMID 33298873, 2020). "CagA, a virulence factor of Helicobactor pylori promotes the expression of FOXM1 by downregulating miRNA 370 in gastric cancer." (PMID 33680951, 2020). "Kaplan-Meier curve analysis using pooled gastric cancer dataset indicate that FOXM1+PLAU+ subgroup predict the worst prognosis, while FOXM1-PLAU- subgroup have the best OS and RFS." (PMID 31949481, 2020). "PVT1 expression in stomach cancer is directly regulated by FOXM1 (Forkhead Box M1) transcription factor." (PMID 32083000, 2020). "MiR-194-5p inhibits cell migration and invasion during gastric cancer progression by down-regulating FoxM1." (PMID 33396321, 2020). "Immunoprecipitation and tandem mass spectrometry (IP-MS) analysis showed that the fork head box M1 (FoxM1) transcription factor interacted with the FBXL2 protein in gastric cancer." (PMID 32293269, 2020). "MicroRNA 630 (mi-RNA-630) inhibits the invasion and migration of gastric cancer cells by targeting FoxM1." (PMID 32035486, 2020). "There were other reports that DIM inhibited cell growth by downregulation of Akt/FoxM1 signaling pathway in gastric cancer, by inactivation of β-catenin/c-Myc in colorectal cancer." (PMID 31396207, 2019). "Not only that, it was also found that FOXM1 contributes to tumor angiogenesis in the study of colorectal and gastric cancer." (PMID 31886176, 2019). "Increasing evidence has suggested that FOXM1 is elevated in many tumors, such as intrahepatic cholangiocarcinoma, oesophageal adenocarcinoma, gastric cancer, cervical cancer, and HCC." (PMID 31886176, 2019). "Bioinformatics study and Luciferase reporter assay indicated that FOXM1 was a target of miR-361-5p and FOXM1 was negatively regulated by miR-361-5p in gastric cancer." (PMID 29435149, 2018). "In conclusion, we found that miR-361-5p suppressed autophagy-induced chemoresistance of gastric cancer cells through targeting FOXM1 via the PI3K/Akt/mTOR pathway, providing a foundation for the mechanism research and treatment of gastric cancer." (PMID 29435149, 2018). "Several lines of evidence have supported that FOXM1 acts as a promoter of angiogenesis and metastasis in gastric cancer." (PMID 30021604, 2018). "PAX8 exerts a tumor-suppressive effect against gastric cancer cells, largely through induction of miR-612 and repression of FOXM1." (PMID 30021604, 2018). "miR-630-mediated downregulation of FOXM1 can inhibit the epithelial-to-mesenchymal transition (EMT) of gastric cancer cells." (PMID 30021604, 2018). "By inducting the expression of miR-612, PAX8 is able to downregulate FOXM1 in gastric cancer cells, consequently leading to reduced cancer cell’s invasive, angiogenic, and metastatic potential." (PMID 30021604, 2018). "Our data showed that the expression of FOXM1 was significantly reduced in PAX8-overexpressing gastric cancer cells, but FOXC2, FOXF1, and FOXL1 remained unchanged." (PMID 30021604, 2018).